BRCA2 (BRCA2 DNA repair associated)
Diseases named in the same sentence as BRCA2 in open-access papers (continued):
Sharing a sentence is not in itself a finding about the gene and the disease.
tumor (continued). "In contrast, 5 patients with BRCA1, BRCA2, and PALB2—all found in patients with tumor types not known to be associated with GPVs in these genes—did not have second hit and are unlikely to respond to PARP inhibitors." (PMID 34792595, 2021). "Regarding BRCA2 C-terminal variants, no linkage with other pathogenic BRCA2 variants, no LOH in tumor tissue and no allelic imbalance in RNA level were confirmed." (PMID 33672545, 2021). "BRCA2 MBC commonly show high tumor grades, do not express progesterone receptors, and are enriched in HER2." (PMID 34298749, 2021). "Generally, it is the tumor suppressor gene and consists of two genes, i.e., BRCA1 and BRCA2; regarding its function, it has been reported that it has a role in DNA repairing mechanism, controlling the growth of the cell and blocking gene mutations, however, each with altered role on the targets." (PMID 34152511, 2021). "Furthermore, a previous study showed that LOH can confer a growth advantage in tumor cells, and the tumor suppressor genes BRCA1 and BRCA2 loci are frequently altered due to allelic imbalance during carcinogenesis in the breast." (PMID 35071399, 2021). "This suggests that possibly homozygous BRCA2 mutant cells can appear not just within the tumor, but outside of it as well, in nontumorous environments such as the vascular system." (PMID 34068254, 2021). "While many functional assays exist to examine HDR or fork protection activities, no specific test for the actual tumor-suppressive functions of BRCA2 has been developed." (PMID 34065235, 2021). "In cases of BRCA2 germline mutations, the prevalence of an IDC-P-positive tumor was markedly higher than those without genetic risk factors, such as familial history (42% vs. 9%)." (PMID 34884926, 2021). "Sixteen of the occult tumours occurred in BRCA1 PV carriers and five in BRCA2 carriers." (PMID 33152107, 2021). "However, both being tumor suppressors, BRCA1 and BRCA2 seem to be involved in different stages of DNA damage response and repair." (PMID 33525353, 2021). "Although the SPN and DT showed neither LOH nor any somatic mutation in the second BRCA2 allele and thus cannot be considered as BRCA-dependent tumors, this study highlights the important role and the new opportunities derived from tumor molecular profiling." (PMID 33810291, 2021). "Increased PD‐L1 mRNA levels in the GR group correlated with BRCA2 mutation status (p = 0.013) but not with BRCA1 mutations and PD‐L1 protein expression in tumor immune cells was significantly higher in those patients with mutations in BRCA2 (p = 0.029)." (PMID 33811746, 2021). "Albeit being isogenic with altered BRCA2 and HR repair status, PEO4 cells may be clonally deviated from PEO1 cells because of tumor heterogeneity during disease progression in the patient." (PMID 33850183, 2021). "The irreversible DSB damage finally resulted in the apoptosis of three BRCA2 monoallelic and biallelic mutant tumor cell lines but not of BRCA2 wild-type cells." (PMID 32980867, 2020). "For instance, in HR-deficient tumour cells, in the absence of BRCA1/BRCA2, PARP1 inhibition has been shown to have cytotoxic side-effects." (PMID 31940791, 2020).
tumor (continued). "RNA-seq data also showed that THZ1 could diminish transcripts of MYC-targeted genes, such as HK2, CDC25A, GLUT1 (SLC2A1), PD-L1 (CD274), BRCA1, and BRCA2, which are important mediators of MYC’s function in tumor metabolism, immune evasion, and DNA repair." (PMID 32690037, 2020). "Synergistic effects were weaker when olaparib was combined with CHK1i and occurred regardless of the BRCA2 status of tumor cells." (PMID 33352723, 2020). "Chimæra analysis suggested that the RB1 locus deletion predates the PTEN mutation and that the BRCA2 and EP300 mutations were acquired in tumor subclones that following RB1 loss, lacked the PTEN mutation." (PMID 32843649, 2020). "No pathogenic variants in BRCA1, BRCA2 or 13 additional HR-related genes, nor BRCA1 promoter hypermethylation or large genomic rearrangements in BRCA1, were detected in the remaining HRD tumor (case 48) nor in the two HRI tumors (case 38 and 39)." (PMID 33003546, 2020). "Pre-clinical work has also shown that mild hyperthermia (i.e., 41 °C-42.5 °C) induces degradation of BRCA2 and inhibits homologous recombination, suggesting HIPEC could be used to sensitize innately HR-proficient tumor cells to PARPi." (PMID 35582446, 2020). "The mixed phenotype of Palb2-KPC tumors could be due to the role of PALB2, as a linker protein between BRCA1 and BRCA2, in BRCA1/2 mediated tumor suppression." (PMID 31877165, 2019). "BRCA1, BRCA2 and NBN act as classical tumor suppressor genes." (PMID 31614901, 2019). "Limitations of our study are the small sample size, the focus on BRCA2 and ATM mutations, the lack of tumor mutational burden measurements, and that no MDSCs were analyzed." (PMID 31549213, 2019). "A meta-analysis showed that women with BRCAm (not specified if somatic mutation carriers are included) OC have an increased OS (BRCA1: HR 0.76, 95% CI: 0.70–0.83; BRCA2: HR: 0.58, 95% CI: 0.50–0.66), regardless of tumour stage, grade, or histologic subtype." (PMID 30909618, 2019). "Deletion patterns can most accurately identify defects of BRCA2 and PALB2, also confirmed in tumor genomes; therefore, a high proportion of deletions with microhomologies may be a good predictor of treatment with PARP inhibitors, cisplatin or carboplatin." (PMID 31727117, 2019). "As dysfunction of BRCA1 and BRCA2 promotes carcinogenesis through promoting genomic instability 16, PALB2 has been hypothesized to be a tumor suppressor gene." (PMID 29321957, 2018). "Olaparib as a single agent is widely used in BRCA1 or BRCA2 mutant tumor cells, but had less effect in CCA cells without BRCA1 or BRCA2 mutations, with a half maximal inhibitory concentration (IC50) close to 10 μmol/L." (PMID 29479816, 2018). "Morphology of ATM-associated tumours was compared with that of 599 patients with no BRCA1 and BRCA2 mutations from a hospital-based series, as well as with data from The Cancer Genome Atlas." (PMID 29665859, 2018). "BRCA1 tumours were largely triple negative and less commonly HER2 positive, whereas BRCA2 tumours were more likely to be hormone receptor positive." (PMID 35693198, 2018).
tumor (continued). "BRCAness has been defined as a phenocopy of BRCA1 or BRCA2 pathogenic mutations, with the existence of an HRR tumour defect in the absence of a BRCA1 or BRCA2 germline mutation." (PMID 29259228, 2017). "Because BRCA2 tumours have higher methylation overall and also worse survival than other MBC cohorts, we also evaluated survival within the BRCA2 carriers, and observed a trend towards worse outcome with higher AMI in this sub-group (HR:3.3, 95% CI: 0.8–9.7, p = 0.1)." (PMID 28893223, 2017). "Cluster analysis showed MBCs arising in BRCA2 mutation carriers were characterised by RASSF1A, WIF1, RARβ and GTSP1 methylation (p = 0.02) whereas methylation in BRCAX tumours showed no clear clustering to particular genes." (PMID 28893223, 2017). "In marked contrast, no tumour growth inhibition was observed on tumours derived from BRCA2 proficient HCT116 cells under the highest dosage." (PMID 28211448, 2017). "Furthermore, combined BRCA2 ASO and olaparib treatment in a tumor cell population with varying degrees of HRR-proficiency prevented the outgrowth of resistant clones." (PMID 26959114, 2016). "However, although we evaluated the nuclear expression of PARP1, BRCA1, and BRCA2 based on the previous reports, the expression of PARP1, BRCA1, and BRCA2 are seen in both the cytoplasm and nuclei of tumor cells." (PMID 27643881, 2016). "When Brca2 is rendered functionally null by CRE-mediated recombination in the epithelial cells using cytokeratin K14 promoter (which is expressed during embryogenesis), tumor incidence is low and tumor latency is very long." (PMID 27490902, 2016). "Due to the frequent LOH in SH individuals, we examined the hypothesis that either BRCA1 or BRCA2 would be lost in each of the TH individuals due to LOH, and that whichever gene was lost could have an impact on their tumor characteristics." (PMID 27836010, 2016). "Preclinical studies have demonstrated that tumor cell lines lacking functional BRCA1 or BRCA2 are sensitive to PARP inhibitors." (PMID 27285752, 2016). "They showed that LOH occurred in two BRCA2 and one BRCA1 tumor." (PMID 27836010, 2016). "BRCA2 siRNA + olaparib treatment decreased both the number and weight of tumors relative to BRCA2 siRNA or olaparib treatment alone (p<0.05), suggesting that combing BRCA2 reduction with PARP1 inhibition may be useful to decrease tumor burden." (PMID 26959114, 2016). "To examine the relevance of physical interaction between BRCA2 and PALB2 on the tumor suppressor function of BRCA2, we generated a cohort of control (wild-type and Brca2Ko/+), Brca2G25R/+, Brca2G25R/G25R, and Brca2G25R/Ko animals and monitored their tumor free survival for 2 yrs." (PMID 27490902, 2016). "Though, in a study that examined methylation status of six tumor suppressor genes that included BRCA1, BRCA2, p14, p16, hMLH, and MGMT in breast (n = 23), other tumor (n = 10), and control tissues (n = 4) suggested that BRCA1, BRCA2, and p14 appeared to be under strong epigenetic silencing." (PMID 25641872, 2015). "In this context, it is tempting to speculate that the tumor suppressor genes BRCA1 and BRCA2, as well as other factors that control the amount of ssDNA/RPA, might protect against HR-mediated genetic instability by regulating the formation of repair centers." (PMID 24615940, 2014). "As a rule, such a tumor develops at a young age (BRCA1-related, at 35–39 years old; BRCA2-related, at 43–54 years old) and characterized by hormone-independent growth, high rate of development in the opposite gland, high degree of malignancy, tendency to relapse, and worse prognosis." (PMID 24325835, 2013). "However, the CN loss of chromosome 13 is intriguing because this affects the loci of well-characterized tumor suppressor genes such as RB1 and BRCA2." (PMID 23577124, 2013). "In general, the carriers of BRCA1 and BRCA2 show higher tumor stage, grade and ER negative tumors, and more metastasis to neighbor vessels relative to those who harbor other gene mutations." (PMID 24312913, 2013).
tumor (continued). "Although certain features, such as viable mice with no tumor formation, are common to conditional deletion of BRCA2 or BCCIP knockdown in neural cells, some features of the BCCIP-CKD mice are distinguishable from the BRCA2 knockout mice." (PMID 22292003, 2012). "However, the representation of carriers is different to that of familial FBC with direct comparison within the kConFab registry showing an increased proportion of BRCA2 male carriers and underrepresentation of BRCA1 male tumours." (PMID 23146383, 2012). "Selected CRC target genes involved in apoptosis (BAX), tumor growth (TGFβRII), WNT pathway (AXIN2, TCF4, WISP3), DNA repair (ATM, ATR, BLM, BRCA1, BRCA2, DNAPKcs, MBD4, MRE11, MSH3, MSH6, RAD50, XRCC2) and PI3-kinase signaling (PTEN) were analyzed for mutations in MSI-positive HGG samples." (PMID 21637783, 2011). "That is, despite the expected differences in the frequency of tumor types between the two sets of carriers, heterogeneity was observed in the distribution of rs299290 genotypes in BRCA1, but not BRCA2, mutation carriers." (PMID 22110403, 2011). "In the final analyses we based the BRCA2 estimates on the proportion of ER-positive and ER-negative tumours in the general population data, due to lack of precision in the age-specific estimates in the BCLC data." (PMID 20482762, 2010). "The fraction of losses in the BRCA1 and BRCA2 tumor groups were not significantly different from The fraction of losses found in the sporadic control group." (PMID 20735817, 2010). "HER2-positive tumours have been shown less common in both BRCA1 and BRCA2 mutation carriers than in noncarriers." (PMID 20482762, 2010). "This suggests a similar mechanism by which these tumours acquire instability and we propose here that this might relate to the involvement of the BRCA1 and BRCA2 genes in error-free DNA repair of double-strand breaks through HR (homologous recombination)." (PMID 19589159, 2009). "Here, we have profiled and examined the patterns of genomic alterations in familial BRCA1 and BRCA2 tumours in the context of sporadic tumours with and without epigenetic silencing of the BRCA1 gene." (PMID 19589159, 2009). "Two of these GII-high subgroups were enriched with either BRCA1- or BRCA2-related tumours whereas the third was not BRCA-related." (PMID 19589159, 2009). "The first grouping labels the 22 tumor samples according to BRCA1 mutation status (positive or negative), and the second grouping labels the samples according to BRCA2 mutation status (positive or negative)." (PMID 18554411, 2008). "This difference may reflect diverse biological behavior and pathways of tumor development among the older and the younger BRCA1 and BRCA2 patients, with impact also on prognosis and survival." (PMID 18053234, 2007). "This difference may reflect different biological behaviour and pathways of tumour development among the older and the younger BRCA1 and BRCA2 patients, with impact also on prognosis and survival." (PMID 15987451, 2005). "BRCA2 cases did not have such distinctive features compared with non-BRCA1/2 tumours or with unselected control tumours." (PMID 15642173, 2005). "In this study, we have evaluated whether tumour histology and immunohistochemistry are influenced by age of onset (menopause status) among families with BRCA1, BRCA2, or non-BRCA1/2 tumours." (PMID 15987451, 2005). "LOH at the BRCA2 region was found in 34% and at RBI in 27% of the tumours." (PMID 8932343, 1996). "These regulatory mechanisms, when considered alongside prior findings and hypotheses, may help explain why BRCA1 and BRCA2 proteins do not exhibit tumor-suppressive functions in most cell types." (PMID 40841483, 2026). "Similarly to BRCA2, a case with germline PALB2 mutation and the absence of somatic LOH had a chromosomally stable tumor." (PMID 41465280, 2025). "Unlike primary tumor cells, tumor cells in brain metastases may harbor mutations in genes such as ERBB2, BRAF, MYC, and BRCA2." (PMID 39780275, 2025).
tumor (continued). "Importantly, our reported incidence may be an underestimation, since we also found BRCA2 methylations in 6 out of 24 TNBC xenografts of which unfortunately, we did only have the primary tumor tissue to analyze for one case." (PMID 39392573, 2025). "However, contrasting findings were reported in another study, where the addition of carboplatin to cabazitaxel was not beneficial for the 36 men (40%) with BRCA2 somatic alterations detected in circulating tumor DNA16." (PMID 40542015, 2025). "In a tumor-agnostic cohort study by Zhou and colleagues, those with BRCA1 or BRCA2 alterations had higher median TMB than their wild-type counterparts (24.6 vs. 5.9, p < 0.001) and comprised a higher proportion with high-TMB tumors (defined as the top 10% of TMB in each tumor type)." (PMID 40426860, 2025). "Each tumor genome was classified according to their HRD and RB1 status, resulting in six groups: BRCA1-HRD & RB1 altered (n = 13); BRCA1-HRD & RB1 wild-type (n = 36); BRCA2-HRD & RB1 altered (n = 8); BRCA2-HRD & RB1 wild-type (n = 20); HRP & RB1 altered (n = 4); or HRP & RB1 wild-type (n = 45)." (PMID 38837893, 2024). "Furthermore, when using VC-8 cell or VC-8 plus BRCA2 cell xenotransplantation tumor models to test sensitivity to the PP2Ai in vivo, we found that the VC-8 tumors lacking BRCA2 were more sensitive to PP2Ai treatment than those expressing wild-type BRCA2." (PMID 37934606, 2024). "PARP inhibition is synthetic lethal with deleterious BRCA1 and BRCA2 mutations because homologous recombination repair (HRR) cannot restore these double-strand breaks, introducing genome instability by nonhomologous end joining or leading to tumor cell death." (PMID 39669575, 2024). "Unlike the other tumor cohorts, BRCA2-/- tumors have 7-fold higher short deletions compared to their controls, which might confound the results." (PMID 38909016, 2024). "In sporadic gastric cancer patients after receiving postoperative adjuvant chemotherapy, BRCA1/BRCA2 expression assessed using IHC and mRNA tests displayed a correlation between BRCA2-elevated expression with advanced tumour stage but not disease-free and overall survival." (PMID 39080120, 2024). "Tumor DNA sequencing in MBC is currently not yet common in clinical practice and is mostly reserved for the determination of the mutational status of the BRCA1/BRCA2, PIK3CA, and, more rarely, the ESR1 and ERBB2 genes." (PMID 36980613, 2023). "In addition, defective BRCA1/BRCA2 in tumor cells may also lead to failure of DSB repair by the HRR pathway, resulting in massive tumor cell death." (PMID 37305685, 2023). "Importantly in 5 patients for whom tumor pathogenic variant analysis was non-contributive, NGS on cftDNA from ascites was informative and uncovered one pathogenic variant of BRCA2 with obvious immediate implications for germline testing and treatment." (PMID 37932736, 2023). "Consequently, excluding grade from the PREDICT score improved the score concordance in CIMBA BRCA2 carriers from 0.601 to 0.610, but also in BCAC BRCA2 carriers from 0.648 to 0.658, suggesting that the tumor grade have little value in the prognosis of BRCA2 carriers." (PMID 37173335, 2023). "In contrast to tumours with BRCA1 or BRCA2 driver events, which harboured 1.6x (95% CI, 1.0–2.4x) and 1.4x (95% CI, 0.9–1.9x) more SVs as well as excess of 10–100 bp deletions (BRCA1, 2.2x; BRCA2, 7.3x), SPOP tumours did not display excess of other somatic mutation types." (PMID 37420249, 2023). "In particular, we found that among four HGOC patients, who underwent upfront germline testing and subsequent tumour sequencing, one showed discordant results, with a germline one-base deletion at a homopolymeric site of BRCA2 that was not identified by the ION Reporter software at tumour testing." (PMID 37179432, 2023). "The study identified 4 (13%) non-BRCA1/BRCA2 tumours with high BRCA1/BRCA2 HRDetect scores that could not be explained by promotor methylation or somatic mutations." (PMID 37316882, 2023).